Y_RNA (Y RNA )
Gene: Miscellaneous RNA gene on chromosome 1 (116,452,536 to 116,452,627, forward strand). Ensembl gene ENSG00000200547.
Homologues: Orthologues: chimpanzee Y_RNA (98% identical), macaque Y_RNA (93% identical), dog Y_RNA (77% identical), tropical clawed frog Y_RNA (71% identical). Paralogues in human: RNY3P1 (87% identical), Y_RNA (87% identical), RNY3 (86% identical), Y_RNA (86% identical), Y_RNA (85% identical), Y_RNA (84% identical), Y_RNA (83% identical), RNY3P16 (82% identical), Y_RNA (82% identical), RNY3P11 (80% identical), RNY3P14 (80% identical), Y_RNA (80% identical), and 91 more.